MMP12 (matrix metallopeptidase 12)
Diseases named in the same sentence as MMP12 in open-access papers (continued):
Sharing a sentence is not in itself a finding about the gene and the disease.
liver fibrosis (25 papers, 2012 to 2025). "It plays a protective role in liver fibrosis, as MMP-12-deficient mice exhibited more liver fibrosis." (PMID 34458001, 2021). "MMP12 was found to regulate elastin degradation, which was linked to the maturity of liver fibrosis." (PMID 31903104, 2020). "Elastin is another ECM protein linked to liver fibrosis progression, and macrophage-derived MMP-12 was shown to mediate its degradation during experimental liver fibrosis." (PMID 32296422, 2020). "MMP‐12 expression has been linked to hepatic fibrosis through the attenuation of IL‐13‐dependent induction of MMP‐2, −9, and −13 in liver." (PMID 32951289, 2020). "We also found that MSCs-sEVs up-regulates MMP12 expression that contributes to tissue remodeling in liver fibrosis." (PMID 40873954, 2025). "IL-4 and IL-6 protect against hepatic fibrosis, IL-4 through secretion of matrix metalloproteinase-12 (MMP-12), and IL-6 through the promotion of proliferation/survival of HSCs." (PMID 38251375, 2024). "Macrophages play a critical role in the resolution of liver fibrosis and are the main source of fibrinolytic matrix metalloproteinases (MMPs), including MMP12 and MMP13." (PMID 39063116, 2024). "Among the hub genes identified from the RNA-seq analysis, Mmp12 caught our attention due to its known roles in inflammation-mediated lung and liver fibrosis." (PMID 35382832, 2022). "IL-4 has shown an anti-fibrotic effect, by activating alternatively activated macrophage, M2, which breakdown extracellular matrix (ECM), leading to resolution of liver fibrosis, by secreting matrix metalloproteinase-12 (MMP-12)." (PMID 36544761, 2022). "Our previous study also illustrated that tumor necrosis factor-α-stimulated gene 6 (TSG-6) derived from MSCs can improve liver fibrosis by modulating M2 macrophages and increasing matrix metalloproteinase 12 (MMP12) expression." (PMID 35858897, 2022). "Additionally, MMP2, MMP3, and MMP9 are highly expressed during the acute phase of tissue damage, and the role of MMP12 in the treatment of mesenchymal stem cells for liver fibrosis has been reported." (PMID 37189708, 2023). "The scope of the present study was to develop a novel enzyme-linked immunosorbent assay (ELISA) for the measurement of a MMP-9 and MMP-12-generated biglycan neo-epitope and to test its biological validity in a rat model of RA and in two rat models of liver fibrosis, chosen as models of ECMR." (PMID 23635022, 2013). "Thus, we conclude that there is infiltration of macrophages to clear apoptotic cell debris and that MMP‐12 expression may be important mediators of hepatic fibrosis in GNMT‐/‐ mice." (PMID 32951289, 2020). "Interestingly, with development of bridging fibrosis at week 52, changes in pathways related to hepatic fibrosis/hepatic stellate cells activation decreased as compared to 24 weeks and were mainly limited to increase in genes for Col4a1, Mmp12, Mmp13 and Vcam1." (PMID 29222421, 2017). "Ly-6Clo subgroup macrophages primarily repair liver fibrosis by upregulating MMPs (MMP9, MMP12, and MMP13), which facilitates the degradation of ECM." (PMID 39635524, 2024). "During the regression phase of liver fibrosis, MoMφs can participate in ECM degradation by secreting MMPs such as MMP9, MMP12, and MMP13, which facilitates the regression of liver fibrosis." (PMID 39635524, 2024). "We found enhanced expression of MMP-12 in the liver and KCs after LNA-anti-miR-132 treatment and overall protection from liver fibrosis." (PMID 34458001, 2021). "The genes labeled as Lcn2, ColIα1, MMp12, and Dbp were upregulated, while Aox4, Cyp2c11, Mup5, LOC100912565, LOC100909412, LOC100360095, and LOC259244 were downregulated in the process of liver fibrosis." (PMID 34597331, 2021). "Liver from hAEC treated mice demonstrated significantly greater expression of MMP-9, which effectively degrades collagen, and significantly less MMP-12, which has been reported to inhibit the production of MMP-9 and increase hepatic fibrosis." (PMID 22719909, 2012).
liver fibrosis (continued). "A CD11bhi/F4/80infLY6Clow macrophage subpopulation was identified during the resolution of liver fibrosis; these special cells do not produce fibrogenic and/or inflammatory factors, but they continue to secrete MMPs, including MMP9 and MMP12, and they upregulate CX3CR1." (PMID 39063116, 2024).
Stroke (24 papers, 2011 to 2026). Sudden impairment of blood flow to a part of the brain due to occlusion or rupture of an artery to the brain. "The gene Mmp12 codes for the protein matrix metalloproteases 12, which has been associated with injury and diseases such as stroke, spinal cord injury, and multiple scoliosis." (PMID 35954192, 2022). "A recent multiancestry genome-wide-association meta-analysis identified a locus in MMP12 associated with atherothrombotic stroke, where the lead SNP was also associated with methylation and protein quantitative trait loci (meQTL and pQTL)." (PMID 32206187, 2020). "Of note was the persistent upregulation of the Mmp12 gene encoding a metalloelastase and Mmp14 encoding a collagenase secreted by fibroblasts in the infarcted area of aged rats at 2 weeks post-stroke." (PMID 24672479, 2014). "Our data suggest associations between the MMP9 R279Q polymorphism and stroke and between the MMP12 N122S polymorphism and combined CHD." (PMID 21887284, 2011). "We found that the protein abundance of seven genes (MMP12, F11, SH3BGRL3, ENGASE, SCARA5, SWAP70 and SPATA20) in the plasma was associated with stroke and its subtypes, and six genes (MMP12, F11, SH3BGRL3, SCARA5, SWAP70 and SPATA20) causally related with stroke and its subtypes." (PMID 41488603, 2026). "The therapeutic benefits of MMP-12 shRNA treatment, especially on neurological and motor function recovery, were more apparent in young males than in young females, presumably because high estrogen levels in females are associated with stroke neuroprotection." (PMID 36267234, 2022). "Studies show that plasma MMP-12 levels are associated with stroke severity and elevated MMP-12 might predict poor outcomes." (PMID 30131754, 2018). "The PWAS identified 7 genes (MMP12, F11, ENGASE, SH3BGRL3, SPATA20, SWAP70, SCARA5) whose cis-regulated plasma protein levels were associated with stroke and its subtypes at a FDR of P < 0.05." (PMID 41488603, 2026). "We identified 7 potential risk genes (MMP12, F11, SH3BGRL3, ENGASE, SCARA5, SWAP70 and SPATA20) of stroke with altered protein abundances in the plasma." (PMID 41488603, 2026). "Previous studies have shown that MMP‐12 causes severe damage to the BBB after ischemic stroke, as well as that MMP‐12 knockdown can alleviate secondary brain injury after stroke." (PMID 37905592, 2023). "MMP‐12 can lead to blood–brain barrier disruption, inflammation, apoptosis, and demyelination after stroke." (PMID 37905592, 2023). "TFPI, CD40, IL6RA and MMP12 were associated with a lower risk of any stroke and any ischaemic stroke, while TMPRSS5 and CD6 was associated with a higher risk of any stroke." (PMID 36253349, 2022). "Suppression of MMP-12 promoted the neurological recovery of stroke-induced male and female rats, although the effect was less apparent in females." (PMID 36267234, 2022). "The most significantly upregulated genes, including Lpl, Spp1, Cd36, Mmp2, and Mmp19, and the most highly enriched genes, including Cd5l, Mmp3, Mmp12, and Mmp13, indicate a pronounced disturbance in lipid homeostasis in infarcts at 7 weeks after stroke." (PMID 34819339, 2022). "In blood, we identified 5 genes (MMP12, SCARF1, ABO, F11, and CKAP2) that had causal relationships with stroke and stroke subtypes." (PMID 35449099, 2022). "Our future studies will examine the effects of suppressing MMP-12 on post-stroke brain damage and neurological recovery in aged animals as well as in animals with co-morbidities, such as hypertension and diabetes." (PMID 36267234, 2022). "In this study we evaluated the pharmacogenetic effects of MMP9 and MMP12 variants on CHD, stroke, HF, combined CHD and CVD, and ACM." (PMID 21887284, 2011). "In light of these promising findings, we investigated whether suppressing MMP-12 in the brain after an ischemic stroke might have a beneficial effect on stroke recovery and therefore be a potential stroke treatment." (PMID 36267234, 2022).
Stroke (continued). "Moreover, genome-wide association studies found that MMP-12 correlates with all ischemic strokes, MMP-1 and MMP-12 with subtypes of stroke, large-artery atherosclerosis, and MMP-8 with small vessel occlusion." (PMID 36553147, 2022). "We hypothesize that the therapeutic effects of suppressing MMP-12 using shRNA will be significantly greater in stroke-induced aged animals, especially in postmenopausal females with low estrogen levels." (PMID 36267234, 2022). "The improved post-stroke neurological and functional outcomes observed in this study may be attributed to the immediate MMP-12 suppression after reperfusion." (PMID 36267234, 2022). "Patients within the fourth quartile of MMP-12–positive macrophages had, compared with patients within the lowest quartile, a 2.4-times increased risk of an MACE and a 3.4-times increased risk of a stroke." (PMID 23316311, 2012). "AZ_628, which screened from CMap analysis, was found to have lower binding energy with Mmp12, Lgals3, Fam20c, Capg, Pkm2, Sdc4, and Itga5 in microglia subcluster 2 and maybe a therapeutic agent for the poor development of microglia subcluster 2 after stroke." (PMID 38067435, 2023). "In addition, in a discovery-validation study of subjects with non-dialysis CKD, MMP-12 was significantly associated with an increased risk of major adverse CV events (fatal or non-fatal myocardial infarction or fatal and non-fatal stroke)." (PMID 35453489, 2022). "Specifically, 3 genes have been associated with atherothrombotic stroke subtype (HDAC9, CDKN (locus 9p21) and TSPAN2), 2 genes with cardioembolic stroke subtype (PITX2 and ZFHX3), and 2 genes with young strokes (ABO and MMP12)." (PMID 29321829, 2018). "Additionally, MMP-3 and MMP-12 expression is significantly upregulated post-stroke: MMP-3 activates pro-MMP-9, amplifying the proteolytic cascade; MMP-12 further exacerbates neurovascular injury by promoting inflammatory cell infiltration." (PMID 41480312, 2025). "Furthermore, 5 different genes (MMP12, ABO, SCARF1, F11, and CKAP2) were discovered in blood, which indicated two distinct pathogenesis for stroke in brain and blood." (PMID 35449099, 2022). "We, therefore, focused further analyses on the proteins with cis-pQTLs only (i.e. TFPI, TMPRSS5, CD40, MMP12, IL6RA, CD6), as these associations with stroke are unlikely to be due to pleiotropy." (PMID 36253349, 2022). "The colocalization evidence at MMP12, was less strong than with the other proteins, with colocalization PP >0.6 and there was no colocalization evidence for IL6RA with stroke, which could be due to violation of the single causal variant assumption of the HyprColoc method." (PMID 36253349, 2022).
aneurysm (21 papers, 2004 to 2025). Bulging or ballooning in an area of an artery secondary to arterial wall weakening. "Loss of MMP12, also known as macrophage metalloelastase, attenuated aneurysm formation in CaCl2-induced AAA model." (PMID 31857579, 2019). "Accordingly, molecular imaging of the MMP-12 active form can inform of the pathogenic process in aneurysm." (PMID 27917892, 2016). "In CaCl2-induced murine aneurysm model, Mmp12 deficiency significantly attenuates aneurysm growth." (PMID 39872985, 2025). "MMP12 is prominently expressed by aneurysm-infiltrating macrophages within the degenerating aortic media of patients with AAA, as well as in the aortas from mice treated with CaCl2 or treated with Ang II and anti-transforming growth factor-β (TGF-β) antibody." (PMID 39872985, 2025). "The genetic deletion of MMP-12 resulted in a reduced elastin degradation and aneurysm severity, culminating in protection from aneurysm rupture and related sudden death." (PMID 38891996, 2024). "MMP-12 is also considered important in aneurysm development because it is selectively produced by macrophages within AAA tissue." (PMID 34123662, 2021). "With the AngII-infused aneurysm model, we found a reduction of Mmp12 expression throughout metformin administration in our study, further evidence for inhibition of inflammation by metformin." (PMID 34617056, 2021). "MMP-12 is activated in atherosclerotic lesions and aneurysms and can promote the activation of other MMPs, which, in turn, destroy other proteins of the extracellular matrix." (PMID 34205079, 2021). "We selected and validated the genes randomly (Lrrc17, Gxylt2, Mfsd2a, Scube and Ank2) and based on their role in aneurysms (Mmp12, Spp1, Ctss) or cardiovascular complications (Mfap4, Igfbp2) or inflammatory signalling pathways (Ccls and Ccrs)." (PMID 30677223, 2019). "The most promising probe was further evaluated for imaging of the active form of MMP-12 in murine models of sterile inflammation and aneurysm." (PMID 27917892, 2016). "Co-immunostaining localized MMP-12 probe binding to MMP-12 positive areas and F4/80 positive macrophages in aneurysm." (PMID 27917892, 2016). "MMP-12 probe binding in aneurysm was further investigated by fluorescence microscopy using a RXP470.1-derived probe incorporating a Cy3 dye (probe 2)." (PMID 27917892, 2016). "Here we describe the development of the first MMP-12-targeted imaging probes and demonstrate their performance in murine models of sterile inflammation and aneurysm." (PMID 27917892, 2016). "Matrix metalloproteinase (MMP)-12 plays a key role in the development of aneurysm." (PMID 27917892, 2016). "Addressing whether targeting a single MMP, e.g., MMP-12, is more effective than panMMP imaging for predicting aneurysm outcome remains to be empirically determined." (PMID 27917892, 2016). "In line with significant upregulation of MMP-12 in aneurysm, in animals injected with probe 3 the fluorescence signal in the aneurysmal left carotid artery was significantly higher than the signal in the control, contralateral artery in tissues harvested at 60 minutes (n = 3, p < 0.01)." (PMID 27917892, 2016). "Significant increase of LDL, cholesterol, triglycerides and circulating inflammatory cells was observed in the Ang II-treated animals, and gene expression studies showed that ICAM-1, VCAM-1, MCP-1, M-CSF, MMP-2, MMP-9 and MMP-12 were upregulated in the aorta of aneurysm-induced mice." (PMID 23826202, 2013). "MMP-12, (macrophage metalloelastase) is up-regulated in atherosclerotic lesions and aneurysms and may contribute to the activation of other MMPs, which, in turn, degrade other extracellular matrix proteins." (PMID 21887284, 2011).
aneurysm (continued). "Increased levels of MMP-2, MMP-3, MMP-9 and MMP-12 have been identified in aneurysm vessel walls." (PMID 15482602, 2004). "Normalized levels of transcripts including MMP12, MT1-MMP (MMP14), and heme oxygenase increased after aneurysm development, particularly in the gene knockout mice, consistent with the invasion of inflammatory macrophages." (PMID 34617062, 2021). "Specific proteinases dissolve elastic fibers, and MMPs are thought to contribute to aneurysm development, including MMP-2, MMP-9, and MMP-12." (PMID 34123662, 2021). "During aneurysm formation, expression of some MMPs, such as collagenase-1 (MMP-1), gelatinase B (MMP-9) or macrophage elastase (MMP-12) is upregulated." (PMID 33799971, 2021). "It has been reported that IFN-γ can protect mice against aneurysm formation and blockade of IFN-γ signaling pathways resulting in abdominal aortic aneurysms primarily due to increased MMP-12 expression." (PMID 25652021, 2015). "Further highlighting mechanistic differences between atherosclerotic and non-atherosclerotic aneurysms, a study from Salarian and colleagues suggested a protective effect of MMP-12 upon AAA through the role as a negative regulator of complement activation." (PMID 38891996, 2024). "MMP12 secreted by macrophages at the onset of inflammation may initiate extracellular matrix remodelling, which, if not controlled, initiates a feedback loop leading to aneurysm formation." (PMID 34091862, 2021).